NOX4 (NADPH oxidase 4)
Diseases named in the same sentence as NOX4 in open-access papers (continued):
Sharing a sentence is not in itself a finding about the gene and the disease.
ovarian carcinoma (continued). "In this study, we also found that combination therapy of NOX4 inhibitor (GKT137831) and afatinib decreased cell viability and had a synergy effect in ovarian cancer cells, which might be a strategy for ovarian cancer treatment." (PMID 34209278, 2021). "In order to explore the role of NOX4 and HIF-1α in the radiation therapy of ovarian cancer, OVCAR3 cells were transfected with shNOX4 or control shNC vector; at 48 h after transfection, cells were irradiated with 6MV X-ray linear accelerator at doses of 0 Gy, 2 Gy, 4 Gy and 6 Gy." (PMID 34209278, 2021). "In conclusion, the novel complex herbal medication JI017 induces apoptosis via Nox4–ROS–Ca2+–ER stress in ovarian cancer cells, and a combination therapy of radiation + JI017 overcomes radioresistance and induces apoptosis via the inhibition of EMT in radioresistant ovarian cancer cells." (PMID 34830138, 2021). "Furthermore, targeting Nox4 using specific siRNA and pharmacological ROS inhibitors, including N-acetylcystein and diphenylene iodonium, blocked apoptosis and ER stress in JI017-treated ovarian cancer cells." (PMID 34830138, 2021). "The downstream genes of NOX4, such as HER3 or/and NF-κB, may play important roles in the regulation of therapeutic sensitivity, which may provide an experimental basis for further investigation into improving ovarian cancer treatment and prognosis in the future." (PMID 34209278, 2021).
Parkinson disease (13 papers, 2015 to 2026). A progressive degenerative disorder of the central nervous system characterized by loss of dopamine producing neurons in the substantia nigra and the presence of Lewy bodies in the substantia nigra and locus coeruleus. "For instance, NOX4 in the hippocampus has been proved to generate massive ROS and cause a redox imbalance, thus contributing to the neurotoxicity of Parkinson's disease (PD) in mouse model." (PMID 41509120, 2025). "By inhibiting NOX4 in a Parkinson’s disease (PD) model, these EVs can reduce the production of reactive oxygen species, thereby mitigating oxidative stress and its inflammatory consequences in dopaminergic neurons." (PMID 40717894, 2025). "In a model of Parkinson’s disease (PD), Nox4 expression was significantly upregulated in the midbrain periaqueductal gray, and blocking Nox4 in this area by infusion of the Nox4 inhibitor GKT137831 resulted in decreased oxidative stress and blunted mechanical and thermal pain responses." (PMID 35740059, 2022). "Trophoblast stem cell‐derived exosomes may reduce ROS production and oxidative stress by delivering miR‐100‐5p, which downregulates the expression of NOX4, thereby ameliorating dopaminergic neuronal injury in Parkinson's disease model mice through the NOX4‐ROS‐Nrf2 pathway." (PMID 39704104, 2025). "Whether changes in the AngII/AT1/Nox4 axis contribute to Parkinson neuropathogenesis is unknown." (PMID 25645462, 2015).
cardiomyopathy (12 papers, 2010 to 2025). A disease of the heart muscle or myocardium proper. "The previous studies of DMD-associated cardiomyopathy found increased induction of NOX4 in the diseased hearts associated with increased fibrosis and functional decline." (PMID 37511627, 2023). "This suggests that NOX4-derived ROS contribute significantly to cardiomyopathy in the early stages of type 1 diabetes, positioning NOX4 as a promising therapeutic target in this context." (PMID 41009041, 2025). "Our previous work confirmed the validity of the Rac1–NADPH oxidase pathway in ELMO1-driven ROS production, as oral inhibition of Rac (EHT1864) or Nox4 each partially mitigated cardiomyopathy, while pan-NADPH oxidase inhibition (VAS3947) markedly prevented it." (PMID 41300434, 2025). "It has been reported that NOX4 underwent extensive alternative splicing in human hearts and that the full-length NOX4 was significantly up-regulated in ischaemic cardiomyopathy." (PMID 38326277, 2024). "ADR treatment increases the expression of NOX2 and NOX4 in the rat kidney, increasing oxidative stress leading to cardiomyopathy." (PMID 35370757, 2022). "NOX4 expression and NOX4-derived ROS are increased ~14 days after the induction of T1D in rats and contribute to the development of cardiomyopathy." (PMID 32133373, 2020). "Together, these findings suggest that NOX4 contributes to the development of cardiomyopathy in the absence of dystrophin, underscoring its pathogenic role in dystrophic heart disease." (PMID 41009041, 2025). "Overexpression of NOX4 further accelerated cardiomyopathy progression in these Mdx mice." (PMID 41009041, 2025).
injury (12 papers, 2012 to 2025). Damage inflicted on the body as the direct or indirect result of an external force, with or without disruption of structural continuity. "In this study, we investigated the role of NOX4 using NOX4 knockout (KO) mice and NOX4 inhibitors in a ventilator-induced lung injury (VILI) model." (PMID 35346198, 2022). "In this study, we investigated the expression of NOX4 as well as the potential therapeutic effects of a NOX4 inhibitor in a ventilator-induced lung injury (VILI) mouse model and pneumonia patients who used a ventilator." (PMID 35346198, 2022). "NOX1 has been reported to worsen hyperoxia-induced acute lung injury in mice, and NOX4 has been suggested to stimulate microglial IL-6 expression and to hamper neurodegeneration after poststroke ischemia reperfusion injury." (PMID 22529530, 2012). "Therefore, this study demonstrates that the treatment targeting ferroptosis and NOX4/NRF2 redox balance will provide a new basis for improving the prognosis of vascular injury-related diseases." (PMID 38336964, 2024). "In this study, GKT137831 inhibited AGE-induced EMP generation, indicating that the NOX-1/NOX-4 inhibitor could serve as a novel therapeutic target in AGE-related vascular endothelial injury." (PMID 29744367, 2018). "This study illustrates the expression profiles of NOX isotypes in the brain after injury, and demonstrates that NOX2, and to a lesser extent, NOX4, may be responsible for the majority of oxidative stress observed acutely after traumatic brain injury." (PMID 24344836, 2013). "The present study found that the expression of hepatic p47phox, gp91phox, and nox4, three NADPH oxidase subunits, was upregulated during alcohol-induced liver injury." (PMID 32184917, 2020). "ROS generation in cisplatin induced kidney injury are contributed to many sources such as NADPH oxidases, NOX2, NOX4 and mitochondrial electron transport chain." (PMID 24454954, 2014).
osteoporosis (12 papers, 2016 to 2025). A condition of reduced bone mass, with decreased cortical thickness and a decrease in the number and size of the trabeculae of cancellous bone (but normal chemical composition), resulting in increased fracture incidence. "Resveratrol alleviates estrogen deficiency-induced osteoporosis by enhancing miR-92b-3p expression, inhibiting Nox4/NF-κB signaling, and decreasing osteoclast activity." (PMID 40243497, 2025). "Furthermore, high levels of NOX4-dependent reactive oxygen species (ROS) have also been found to be responsible for age-related bone loss, suggesting NOX4 as a potential therapeutic target to counteract osteoporosis during aging." (PMID 39846667, 2025). "NOX4 specifically has been linked to osteoporosis, inflammatory arthritis and osteoarthritis." (PMID 38379095, 2024). "Indeed, NOX4-deficient mice are characterized by increased bone density and trabecular thickness, suggesting this enzyme is a potential therapeutic target to counteract osteoporosis." (PMID 39846667, 2025). "The expression of Nox4 increases during the differentiation and maturation of osteoblasts, and the formation of Ocn increases after Nox4 is activated, which can induce osteoporosis." (PMID 35581617, 2022). "The novel pyrazole derivative Ewha-18278 was developed to selectively inhibit NOX1, NOX2, and NOX4 to treat osteoporosis." (PMID 31533299, 2019). "In the beginning stage, we developed a novel lead compound, #1, for selective inhibition of NOX1 and NOX4 in the treatment of osteoporosis." (PMID 31533299, 2019). "Ovariectomy triggers Nox4 overexpression followed by ROS overproduction and NF-κB activation as well as mitochondria dysfunction, which initiates and accelerates osteoporosis via the Nox4/ROS/NF-κB pathway." (PMID 28588482, 2017). "However, although NOX4 has been proposed as a promising therapeutic target for osteoarthritis and osteoporosis, its involvement in their pathogenesis needs further investigation." (PMID 40956314, 2025). "NADPH Oxidase 4 (Nox4) is primarily secreted by osteoclasts, and its activation promotes osteoclast differentiation and maturation, promoting bone resorption and, ultimately, osteoporosis." (PMID 37239124, 2023). "Suppression of miR-92b-3p expression increased Nox4 and NF-κB levels, decreased Smad7, BMP2, and RUNX-2 genes and protein expression, and inhibited BMSC proliferation and osteoblast differentiation, resulting in worsened osteoporosis." (PMID 37239124, 2023). "Suppression of miR-92b-3p expression increased NADPH oxidase 4 (Nox4) and NF-κB levels, decreased Smad7, BMP2, and Runx2 gene and protein expressions, and inhibited bone marrow mesenchymal stem cell (BMSC) proliferation and osteoblast differentiation, resulting in more severe osteoporosis." (PMID 37239124, 2023). "In addition, western blotting analysis showed reduced expression of NOX4 and increased expression of SIRT1 and PTX3 in both experimental groups, although with more pronounced effects in osteoarthritic patients, highlighting lower treatment efficacy in the presence of osteoporosis." (PMID 40956314, 2025).
type 1 diabetes (12 papers, 2012 to 2025). "A previous study demonstrated that the administration of antisense oligonucleotides for Nox4 in type 1 diabetic rats improved renal hypertrophy and matrix expansion." (PMID 37109492, 2023). "It has been reported that mTORC2 plays a critical role in Nox4-derived ROS generation and podocyte apoptosis, which contributes to urinary albumin excretion in type 1 diabetes." (PMID 33046439, 2021). "In another study, researchers found that, upon induction of type 1 diabetes with streptozotocin, Nox4 knockout rats exhibited significantly lower basal intracellular Ca(2+) levels in podocytes and less DKD-associated damage than wild type rats did." (PMID 33071778, 2020). "In the present study, mesenteric arteries from Nlrp3–/– mice with type 1 diabetes displayed decreased expression of Nox4 and reduced ROS levels." (PMID 32009974, 2019). "Of importance, inhibition of the small GTPase RhoA, by fasudil or statins, reduces renal Nox4 protein expression in streptozotocin-induced type 1 diabetes as well as in db/db mice." (PMID 27649495, 2016). "Considering the view that both NOX4 and NOX5 appear to play roles in DKD, we examined the pathogenic role of NOX5 in the presence or absence of NOX4 expression using endothelial cell (EC)-specific NOX5 transgenic mice in a streptozotocin (STZ)-induced insulin-deficient type 1 diabetes model." (PMID 38671844, 2024).
chronic obstructive pulmonary disease (11 papers, 2019 to 2025). A chronic and progressive lung disorder characterized by the loss of elasticity of the bronchial tree and the air sacs, destruction of the air sacs wall, thickening of the bronchial wall, and mucous accumulation in the bronchial tree. "Of note, we have previously shown that NOX4 is selectively upregulated in patients with AF and that NOX4-derived oxidative stress triggers an AF-like cardiac arrhythmia in a zebrafish model." (PMID 39199217, 2024). "Embryos overexpressing Nox4 exhibit cardiac arrhythmia, increased production of O2•− and H2O2, and redox-sensitive CaMKII activation." (PMID 37891912, 2023). "Luteolin alleviated inflammation and oxidative stress in chronic obstructive pulmonary disease via NOX4‐mediated nuclear factor‐kappa B signaling." (PMID 37102667, 2023). "An augmented NOX4 expression is correlated with the increased pulmonary vascular wall volume in lung tissues isolated from patients with chronic obstructive pulmonary disease undergoing lung surgery." (PMID 34440716, 2021). "Attenuation of embryonic cardiac arrhythmia and oxidative stress was observed with PEG SOD and NOX4 inhibitors, while CaMKII inhibitors abolished the phenotype." (PMID 37891912, 2023). "Interestingly, MitoTEMPO treatment prevented NOX4-induced H2O2 production, indicating that mitochondrial oxidative stress plays a role in cardiac arrhythmia." (PMID 33585462, 2020). "An increased expression of NOX4 and TGF-β was found to be correlated with the increased volume in both airway smooth muscle mass and epithelial cells of small airways in patients with chronic obstructive pulmonary disease (COPD)." (PMID 33308225, 2020).
diabetic cardiomyopathy (11 papers, 2012 to 2025). Diabetic cardiomyopathy is a disorder of the heart muscle in people with diabetes. "Daidzein is a good antioxidant and anti-inflammatory ingredient; basic experiments showed that daidzein mitigates the progression of diabetic cardiomyopathy by inhibiting NOX-4 induced oxidative stress in cardiac tissues." (PMID 35600966, 2022). "However, more studies are needed to elucidate the effective role of NOX4 in diabetic cardiomyopathy." (PMID 36721814, 2023).
lung diseases (11 papers, 2016 to 2025). "The existing clinical trials for other indications such as liver and pulmonary diseases, provide a foundation for considering NOX4 inhibition as a therapeutic strategy in cardiovascular diseases." (PMID 41009041, 2025). "Both negative and positive feedback are influential in regulating NOX4 expression in many disorders, including pulmonary diseases, kidney disease, and cancers." (PMID 39000202, 2024). "Similar modulation of NOX4 was identified in previous studies showing that NOX4 expression was upregulated in pulmonary diseases, cardiovascular diseases, kidney injury and other conditions." (PMID 35606794, 2022). "Nicotinamide adenine dinucleotide phosphate (NADPH) oxidase [NOX] enzymes serve several hemostatic and host defense functions in various lung diseases, but the role of NOX4 signaling in tuberculous pleurisy is not well understood." (PMID 30669315, 2019). "Mutations affecting function of the human NOXs cause severe diseases such as chronic granulomatous disease (NOX2), and NOX dysregulation has been attributed to cardiovascular, neurological disorders (NOX2, NOX4), and pulmonary diseases and cancers (NOX1 and NOX4)." (PMID 35998431, 2022). "Accordingly we speculate that metformin regulation of NOX4 expression can be a promising anti-fibrotic modality of treatment for fibrotic lung disorders affected by TGF-β." (PMID 27576730, 2016). "Given functions of NOX4 in ROS production and pathogenesis of pulmonary disorders, as well as ASM hyperplasia and hypertrophy in asthmatic airway remodeling, we therefore hypothesized that the NOX4 may also have an implication in ASM remodeling of small airway of COPD lung." (PMID 27656649, 2016).
metabolic syndrome (11 papers, 2012 to 2025). A cluster of metabolic risk factors for CARDIOVASCULAR DISEASES and TYPE 2 DIABETES MELLITUS. "The minor A-allele of the NOX4 SNP was inversely associated with the frequency of metabolic syndrome (MS) in the male population (odds ratio (OR): 0.15; 95% confidence interval (CI): 0.03 to 0.79; P = 0.025)." (PMID 25888935, 2015). "We provide evidence that NOX4 is essential for the vascular function of resistance arteries, particularly under dyslipidemia conditions." (PMID 38790608, 2024). "In the present study, we provide evidence that Nox4 is important for the maintenance of vascular function in resistance arteries under conditions of dyslipidemia." (PMID 38790608, 2024). "In human left internal mammary arteries (LIMA) from patients undergoing coronary bypass surgery, we also found evidence for higher NOX4 expression in patients with dyslipidemia." (PMID 38790608, 2024). "Our findings link the interaction between dyslipidemia and cancer metastasis and provide new insight into coincident ANGPTL4 and NOX4 expression as a potential diagnostic biomarker and therapeutic target for CRC therapy." (PMID 32641980, 2020). "Development of first-in-class series of NOX4 inhibitors for the potential treatment of fibrotic diseases, cardiovascular and metabolic syndromes is in progress." (PMID 23049784, 2012). "We hypothesized that NOX4 is of functional importance in resistance arteries and perivascular adipose tissue under dyslipidemia conditions." (PMID 38790608, 2024). "We observed increased NOX4 expression in arterial vessels from mice and humans under dyslipidemia." (PMID 38790608, 2024). "We detected elevated NOX4 expression in murine and human vessels under dyslipidemia." (PMID 38790608, 2024). "Resultantly, the cardioprotective effects of the low-level activity of these enzymes (NADPH oxidase 4, iNOS, and eNOS) are converted by the metabolic syndrome milieu factors to a cardiovascular damaging status via an enzymatic interplay of self-sustaining high-level activity." (PMID 34200262, 2021). "Thus, this study provides a new understanding of how the dyslipidemia-induced ANGPTL4/NOX4 axis contributes to CRC metastasis." (PMID 32641980, 2020). "In conclusion, vascular function of resistance arteries was dependent on Nox4-derived H2O2, especially under dyslipidemia conditions." (PMID 38790608, 2024). "However, in this experiment, we did not evaluate the identification of the Nox2/ Nox4 ratio because our primary object was to investigate the effect of intermittent high glucose (models of impaired glucose tolerance and metabolic syndrome) on endothelial senescence." (PMID 25879533, 2015).